FLT3 (fms related receptor tyrosine kinase 3)
Diseases named in the same sentence as FLT3 in open-access papers (continued):
Sharing a sentence is not in itself a finding about the gene and the disease.
tumor (continued). "Sorafenib and sunitinib effectively inhibit various tyrosine kinases such as FMS-like tyrosine kinase 3 (FLT3), KIT, and RET, suppressing tumor growth and angiogenesis by inhibiting VEGFR2/3 and PDGFRβ." (PMID 40821121, 2025). "Altogether, these results show that gilteritinib can more effectively decrease tumor burden and target treatment-resistant KF cells, thereby improving response to VXL chemotherapy or venetoclax in FLT3-expressing ETP-ALL." (PMID 39849166, 2025). "Several other PROTACs targeting FLT3 alone have also been shown to degrade the kinase, reduce oncogenic FLT3 ITD signalling, and decrease cell proliferation in vitro, as well as exhibiting anti-tumour activity in vivo." (PMID 40941028, 2025). "Specifically, BRD4, FLT3, and SIAH2 were upregulated in tumor tissues, whereas CS and PIK3CA were downregulated." (PMID 40696656, 2025). "In FLT3 ITD-expressing cell lines and AML samples, 2-DG treatment leads to tumour cell growth inhibition and induces apoptosis." (PMID 40941028, 2025). "In agreement with the in vitro results, coadministration of A485 and quizartinib enhanced the inhibition of H3K27Ac, c-Myc and FLT3 signaling, as evidenced by the reduced phosphorylation of STAT5 and ERK in tumor tissues." (PMID 39885312, 2025). "Since PTPs affect FLT3 oncogenic signalling, modulation of PTP activity, such as inhibition of proto-oncogenic PTPs or enhancing the activity of tumour-suppressive PTPs, can directly influence the phosphorylation and activity of FLT3 proteins." (PMID 40941028, 2025). "FLT3-specific CAR-T cells eradicated FLT3-positive AML cells successfully and enhanced their anti-tumor effects with the inhibitor crenolanib." (PMID 38892913, 2024). "Regarding gene amplification, EWSR1, FLT3, GPC3, HIF1A, HLF, and MEN1 have been reported in CaPa and other neoplasias as well." (PMID 38397997, 2024). "Gold nanoparticles loaded with FLT3 inhibitors had an increased transmembrane delivery in AML cells, and the in vitro evaluation indicates that the FLT3-IDT gene was downregulated, leading to tumor cell suppression." (PMID 38799169, 2024). "A tumor microenvironment (TME) with high immune infiltration and rich in T‐cell exhaustion markers was observed in the FLT3‐high group." (PMID 38327131, 2024). "Among all the 12 signature genes in the risk score model, we found that most of the genes were statistically different between tumor tissues and normal controls, and in particular, two genes (PPARGC1A and FLT3) were decreased in the tumor tissue." (PMID 38468074, 2024). "Results showed that the mRNA levels of BNIP3, CYCS, RRAGD, CD44, EIF4E, MAP4K1, and LIN28B were higher in tumor samples, whereas the mRNA levels of PPARGC1A and FLT3 were higher in normal samples." (PMID 38468074, 2024). "VEGF receptors (KDR, FLT4, FGFR1, and FLT3) and FGF receptors support tumor angiogenesis, providing essential nutrients for growth." (PMID 39273340, 2024). "Presumably, the exhausted Flt3m-CAR T-cells and Flt3-CAR T-cells can interact with tumor cells through the Flt3-ligand:Flt3 receptor interface, blocking access to active Flt3m-CAR T-cells and Flt3-CAR T-cells." (PMID 37108788, 2023). "CSF1R, FGFR1, FLT3, and KDR are related to the tumor microenvironment, and ERBB4, STK11, PTEN, and NPM1 are related to proliferation-related factors." (PMID 36780540, 2023). "Not only can it directly inhibit tumor growth through KIT and FLT-3 inhibition of RAF/MEK/ERK signaling pathway, but also indirectly blocking tumor angiogenesis by blocking VEGFR and PDGFR with a dual anti-tumor effect." (PMID 37803421, 2023). "The in vivo efficacy of emavusertib on leukemic tumor burden was evaluated in the human THP-1 monocytic (AML, FLT3-wt) cell line model." (PMID 37954584, 2023). "Sorafenib has tumor-agnostic efficacy in patients with tumors harboring genomic alterations in PDGFRA/B, VEGF-Rs, Flt-3, KIT, FGFR1 or the RAF/MEK/ERK pathway." (PMID 37444551, 2023).
tumor (continued). "Pacritinib (SB1518), a TKI with potent FLT3 and JAK2 inhibitory activity, effectively reduced tumor growth in the MOLM-13 mouse xenograft model." (PMID 36982453, 2023). "The compound showed good liver microsomal stability, poor antiproliferative effect against FLT3-wt tumor cells, low toxicity to normal cells and weaker inhibitory activity against c-KIT compared with the FLT3 inhibitor gilteritinib in a zebrafish model." (PMID 36770891, 2023). "In situ vaccination combining Fms-like tyrosine kinase 3 (Flt3), poly-ICLC, and radiotherapy induced antitumor CD8 + T cell responses in patients with advanced stage indolent NHL, some of whom had a heavy tumor burden." (PMID 37475035, 2023). "In a preclinical study, a second-generation FLT3 4-1BB-CD3-CAR T-cell demonstrated the ability to recognize and eliminate FLT3+ tumor cells." (PMID 38201469, 2023). "Recent several studies have showed that FLT3-ITD-induced ROS generation can result in the oxidation of tumor suppressor genes and of DEP-1 phosphatase which acts as negative regulator of FLT3." (PMID 37391442, 2023). "According to the gene fusion and rearrangements of PDGFRA, PDGFRB, JAK2, FGFR1, ETV6:ABL1, and FLT3, WHO5 defined these types of neoplasms as a separate class." (PMID 37371477, 2023). "The anti-leukemic effect was confirmed in primary AML cells expressing FLT3-ITD and in xenograft models obtained by MV4-11 cell inoculation, by a reduction in tumor growth." (PMID 36770891, 2023). "Our results indicate that PSMA3-AS1 is elevated in FLT3-ITD+ AML tissues and cells and can promote cell proliferation and tumor growth." (PMID 37088992, 2023). "In this context, this study first found that IGF2BP2, a reading protein in m6A, is highly expressed in FLT3-ITD + AML patients and cells, and its regulatory role in tumor progression and glycolysis." (PMID 37060505, 2023). "CT053 (free-base form of CT053PTSA) inhibited MET, AXL, VEGFR2, FLT3 and MERTK phosphorylation and suppressed tumor cell angiogenesis by blocking VEGF and HGF, respectively, in vitro." (PMID 36341335, 2022). "In this report, we evaluated the anti-tumor effect of ASP1235 in combination with venetoclax or venetoclax plus azacitidine for THP-1 cells, which are AML-derived cells expressing both FLT3 and Bcl-2." (PMID 36537913, 2022). "When targeting anti-angiogenesis, MTDs can simultaneously target multiple proteins that promote tumor growth such as RET, FLT3, and BRAF, which contribute to the overall anti-tumor effect." (PMID 35463356, 2022). "Kinase profiling using KINOMEScan has revealed that, in addition to targeting FLT3/AURK signaling pathways, MET and AXL, two kinases that play a critical role in HCC tumor progression, invasion, and metastasis, were potently inhibited by DBPR114." (PMID 35062934, 2022). "Remarkably, by examining samples collected at early time points, we also found that the FLT3-specific IgG developed rapidly in tumor-bearing mice, as early as 10 days after the first VRP-FLT3 vaccination." (PMID 35686131, 2022). "It is a multikinase inhibitor targeting VEGFR1-3, MET, the TAM family of kinases (TYRO-3, AXL, MER), RET, ROS1, KIT, TRKB, FLT-3, and TIE-2, which are mostly involved in tumor growth, angiogenesis, and immune regulation." (PMID 36612019, 2022). "MBP-11901, a multi-RTK inhibitor, was shown to inhibit tumor growth and kill HCC by targeting VEGFR2, c-KIT, PDGFRβ, and FLT3." (PMID 35454900, 2022). "In preclinical studies, the FLT3-targeted CAR-T cells successfully eliminated FLT3 positive AML cells, and the FLT3 inhibitor crenolanib promoted their anti-tumor effects." (PMID 35757715, 2022).
tumor (continued). "Low infiltration of cDC1s observed in some tumor types might be a consequence of a systemic suppression of hematopoiesis in the bone marrow, or a local inhibition by the reduced production of growth factors, like FLT3 and G-CSF which are important for differentiation, expansion and survival." (PMID 36230990, 2022). "A pharmacodynamic study in tumor bearing mice has also shown that CDDD11-8 works by potently inhibiting CDK9 and FLT3, similar to the in vitro finding." (PMID 35267421, 2022). "FLT3-harboring VRP (VRP-FLT3) vs control VRP (VRP-Ctrl, vector alone) were administered by footpad injection as therapeutic vaccines on days 4 and 18 after tumor challenge." (PMID 35686131, 2022). "siRNAs directed specifically against two common mutated genes in the AML, the DNA-methyltransferase DNMT3A and FLT3-ITD lead to a reduction of clonal growth in vitro in AML cell lines and inhibit tumor growth in vivo in xenotransplanted cell lines." (PMID 36457063, 2022). "So far, panels of binders have been isolated against different viral and tumor targets, including the SARS-CoV-2 RBD, HIV-1 ENV protein, mesothelin and FLT3." (PMID 35464476, 2022). "Inhibitors that target MET, AXL, VEGFR-2, FLT3 and MERTK are becoming research and development hotspots owing to their effect on promoting tumor development and progression." (PMID 36341335, 2022). "Bispecific CAR T cells recognize two tumour antigens specific to AML, thereby creating synergistic effects to target all AML cells expressing either NKG2DLs or FLT3." (PMID 35246156, 2022). "Many tumor surface antigens are potential targets of BsAbs, such as CD123, CD33, FMS-like tyrosine kinase 3 (FLT3), C-type lectin domain family 12 member A (CLEC12A), and Wilms' tumor gene 1 (WT1)." (PMID 33941237, 2021). "Sorafenib is a multikinase inhibitor that targets the Raf/MAPK/ERK signaling pathway, interfering with the tyrosine kinases VEGFR-2/3, PDGFR-β, B-Raf, c-Raf, FGFR1, Flt3, c-KIT, RET, and p38 α, and induces tumor cell apoptosis in HCC." (PMID 33808407, 2021). "Treatment with FLT3 L/poly I:C, which induces the activation of CD103+ cDC1s at tumour sites and induce proliferation of naïve CD8 T cells and generated CTLs, has been shown to enhance antitumour responses." (PMID 34059019, 2021). "This drug not only directly suppresses tumor cells proliferation by blocking RAF/MEK/ERK and JAK/STAT signaling pathways, but also inhibits tumor angiogenesis by targeting VEGFRs, PDGFR-β, c-Kit, FLT3, RET." (PMID 34381735, 2021). "Among MMRp CRCs, we found MYC and FLT3 amplification in one tumor (T32), MYC and CCND1 amplification in 1 tumor (T36), and EGFR amplification in one tumor (T38)." (PMID 33435234, 2021). "Sunitinib, a MKI targeting VEGFR1,2,3, Kit, PDGFRA/B, FLT-3 and RET has also shown efficacy in the reduction of the primary tumor proliferation and the tumor vasculature in cell-derived osteosarcoma mouse models." (PMID 34069999, 2021). "In mouse xenograft models of FLT3-ITD mutant AML, Gilteritinib alone or ATO alone both reduced tumor size, while combination of Gilteritinib with ATO produced a profound treatment." (PMID 32565734, 2020). "It inhibits the activity of target enzymes/factors located in tumour cells (CRAF, BRAF, V600E BRAF, c-KIT and FLT-3) and in tumour vasculature (CRAF, VEGFR-2, VEGFR-3 and PDGFR-β)." (PMID 32016844, 2020). "Meanwhile, other groups have tried to improve DC efficacy with the use of local induction of FMS-related tyrosine kinase 3 (FLT3), whose signaling is key to the recruitment and expansion of DCs at the tumor site." (PMID 33027976, 2020).
tumor (continued). "In a patient-derived FLT3-ITD xenograft model, the combination of venetoclax and quizartinib, a second-generation FLT3 inhibitor, had a greater anti-tumor activity compared to quizartinib or venetoclax monotherapy." (PMID 33198085, 2020). "Another multi-kinase inhibitor sunitinib, an anti-PDGFRα/β, VEGFR1/2/3, KIT, FLT3, CSF- b1R and RET, has been shown to decrease primary tumor proliferation and reduce tumor vasculature in cell-derived intratibial OS model in SCID mice." (PMID 29520051, 2018). "miR-155, for example, is upregulated respect to healthy subjects having an oncogenic function in AML FLT3-ITD subgroup; by contrast, in different AML subsets, it was demonstrated to have a tumor suppress function." (PMID 29401684, 2018). "Therefore, CAR-T cell that recognizes FLT3 may induce on-target/off-tumor toxicities." (PMID 29716633, 2018). "In SCID/beige mice bearing MV-4-11 tumors (FLT3-ITD+) treated with SEL24-B489, we noted marked dose – dependent tumor reduction (67%, 74% and 82% tumor growth inhibition (TGI) for 50, 75 and 100 mg/kg daily doses, respectively)." (PMID 29682194, 2018). "This is consistent with a model in which DEK-NUP214 was an early genomic alteration, present in all tumor cells at diagnosis, while the FLT3-ITD was acquired later and present in approximately 80% of the tumor." (PMID 30262806, 2018). "Sunitinib is an oral, multitargeted TKI targeting VEGFR, Kit, platelet-derived growth factor (PDGFR), FMS-like tyrosine kinase 3 (FLT3) and RET on tumor cells, tumor neovasculature and pericytes." (PMID 30680072, 2018). "in vitro, crotonoside exhibited potent anti-proliferative activities against FLT3-driven AML cell line MV4-11, and exhibited low toxic effects in normal cells and other tumor cell lines." (PMID 29262547, 2017). "Additional in vivo studies have demonstrated that blocking AXL can suppress the growth of FLT3-ITD AML, decrease tumor size, and block the activation of cellular survival pathways while upregulating the apoptotic pathway." (PMID 28516360, 2017). "Several small-molecule FLT3 inhibitors, including Sunitinib, Ponatinib, PKC-412, Sorafenib, and AC220, are being evaluated in the recent clinical trials, showed promising anti-tumor activity." (PMID 29262547, 2017). "Expression of SLAP2 controls oncogenic FLT3-ITD-induced cell proliferation, colony and tumor formation through regulation of AKT, ERK, p38 and STAT5 signaling." (PMID 27458164, 2016). "To understand the role of SLAP2 in FLT3-ITD mediated cellular transformation we used colony formation assays in semi-solid medium and tumor formation capacity in xenografted mice." (PMID 27458164, 2016). "In FLT3-ITD positive AML patient primary cells and a FLT3-ITD-positive xenograft model, A674563 displayed great anti-tumor activity." (PMID 27074558, 2016). "PI3KD/V-IN-01 is particularly potent against FLT3-ITD positive AML cells and exhibits significant anti-tumor activity in vivo." (PMID 27447747, 2016). "SLAP2 over expression in murine proB cells or myeloid cells inhibited oncogenic FLT3-ITD-mediated cell proliferation and colony formation in vitro, and tumor formation in vivo." (PMID 27458164, 2016). "In a systemic FLT3-ITD+ AML mouse model, treatment with NT1721 reduced tumor burdens by > 95% compared to the control and significantly increased survival times." (PMID 27863389, 2016). "BEX1 localized to the cytosolic compartments and overexpression of BEX1 resulted in decreased cell proliferation and colony formation, delayed tumor formation and increased apoptosis by inhibiting AKT signaling induced by FLT3-ITD." (PMID 26046670, 2015). "Overexpression of BEX1 in mouse pro-B and myeloid cells resulted in decreased FLT3-ITD-dependent cell proliferation, colony and tumor formation, and in increased apoptosis in vitro and in vivo." (PMID 26046670, 2015).
tumor (continued). "Nevertheless, sorafenib was highly anti-angiogenic in our experiments, presumably due to inhibition of its other tyrosine kinase targets important for tumor angiogenesis, including Raf, c-Kit, PDGFR-β and Flt-3." (PMID 24965046, 2014). "After bi-weekly administrations of IgG, PRL-3 or FLT3 mAbs over 12–14 days, PRL-3 mAb-treated mice showed a significant reduction of liver and spleen sizes, indicative of reduced tumour burden." (PMID 23929599, 2013). "Sorafenib has been successful, because it targets proteins of multiple signaling pathways simultaneously—VEGFR2, VEGFR3, PDGFR, Flt-3, c-kit and the Raf/MEK/ERK pathway—to inhibit tumor growth and to induce apoptosis of tumor cells." (PMID 26835673, 2013). "Collectively, our results here demonstrate a significant benefit of PRL-3 immunotherapy in reducing FLT3-ITD AML cell engraftment in bone marrow and tumour burden, as well as in prolonging survival." (PMID 23929599, 2013). "The other target genes, FLT3, CSF1R, PDGFRB, AXL and MET showed lower expression levels in the tumor tissue compared to normal tissue except AXL in NF1 associated GIST." (PMID 21171987, 2010). "In addition, in an FLT3-ITD-positiveAML patient-derived xenograft (PDX) mouse model, the CC-90009 and quizartinibcombination showed significantly higher anti-tumor efficacy and prolongedoverall survival compared to either treatment alone." (PMID 41270153, 2025). "Its mechanism of action primarily involves inhibiting multiple angiogenesis and tumour proliferation-related signalling pathways, including: VEGFR-2, VEGFR-3, platelet-derived growth factor receptor-β (PDGFR-β), RAF-1,c-Kit, and FMS-like tyrosine kinase 3 (Flt-3)." (PMID 41195336, 2025). "Additionally, the coadministration of A485 and quizartinib enhanced the inhibition of H3K27Ac and c-Myc expression, as well as FLT3 downstream signaling, including STAT5 and ERK phosphorylation, in tumor tissues from MV-4-11/quizartinib xenografts." (PMID 39885312, 2025). "Combined with the clinical correlation analysis, we hypothesized that neferine may affect the cell cycle of GC through FLT3, CDK6, and SYK to generate an anti-tumor effect." (PMID 40138292, 2025). "In parallel with in vitro results, results in the animal model also indicated the Prime-Fect complexes of FLT3 siRNA to be effective in reducing the systemic tumor burden, unlike the PEI1.2k-PHPA-Lin9 complexes." (PMID 39858509, 2025). "Some studies suggested that loss of HOXB3 correlates with the development of hormone receptor negative breast cancer, or act as tumor suppressors through FLT3-ITD driver in AML." (PMID 38254070, 2024). "In mouse xenograft models of FLT3-ITD AML, decitabine was effective to reduce the tumor volume." (PMID 38696033, 2024). "Based on the genetic mutation profile and the deregulation of certain signaling pathways, such as FLT3 internal tandem duplication (FLT3-ITD), c-KIT, PI3K/AKT pathway, and non-coding RNAs, different targeted therapies have been developed to induce tumor-specific killing effect in AML." (PMID 38637730, 2024). "The anti–FLT3-ITD affinity of compound 7 was assured via establishing the in vivo MV4-11 xenograft model where compound 7 is given a 30 mg/kg dosage, resulting in significant tumor growth suppression." (PMID 37438819, 2023). "Eight cases with tumor depth >10 mm showed mutations in CSF1R, ERBB4, FLT3, KDR, and NPM1, regardless of lymph node metastasis." (PMID 36780540, 2023). "Next, CPL304110 selectivity was analyzed on seven kinases; the results showed that CPL304110 had the highest activity against kinases that share homology with FGFRs (KDR and PDGFRβ) and others that play an important role in tumor development and progression (AURKA, FLT3, IGF1R, JAK2, and TRKA)." (PMID 38282676, 2023). "Although gilteritinib did not influence the in vitro reduction in tumor growth or induction of apoptosis, stimulation of the FLT3 ligand can raise the chance of resistance to other FLT3 inhibitors." (PMID 37297842, 2023).